MYEOV (myeloma overexpressed)
Synonyms: OCIM
Tractability: PROTAC: ubiquitination databases record sites on it.
Gene: Protein-coding gene on chromosome 11 (69,294,129 to 69,341,682, forward strand). Ensembl gene ENSG00000172927.
Subcellular location (Human Protein Atlas): Nucleoplasm; Vesicles
Gene Ontology:
Molecular function: protein binding
Genetic constraint (gnomAD): Loss-of-function variants: 4 observed, 4.81 expected, observed/expected ratio (o/e) 0.83, 90% interval 0.4 to 1.72. That is too few expected variants to judge how well the gene tolerates losing a copy. Missense variants: 400 observed, 417.63 expected, observed/expected ratio (o/e) 0.96, 90% interval 0.88 to 1.04. Synonymous variants: 180 observed, 173.65 expected, observed/expected ratio (o/e) 1.04, 90% interval 0.92 to 1.17.
Homologues: Orthologues: chimpanzee MYEOV (96% identical).
Diseases named in the same sentence as MYEOV in open-access papers:
MYEOV is named in the same sentence as 33 diseases in open-access papers, as found by Europe PMC text mining. Sharing a sentence is not in itself a finding about the gene and the disease. The quoted sentences say what the papers report.
myeloma (14 papers, 2015 to 2025). "Myeloma overexpressed gene (MYEOV) was initially reported as a gene associated with multiple myeloma." (PMID 41186354, 2025). "SNP rs12418451 is also ~126 kb upstream of MYEOV, an oncogene that includes variants implicated for multiple cancers, including multiple myeloma, breast cancer, colon cancer, and esophageal squamous cell carcinoma." (PMID 25789475, 2015). "Whole exome sequencing of blood and tissue samples highlighted myeloma overexpressed gene (MYEOV), B melanoma antigen family member (BAGE), and N-acetylated-alpha-linked acidic dipeptidase 2 (NAALAD2) as potential mutated genes related to Zinner syndrome." (PMID 40069600, 2025). "The overexpressed gene MYEOV in multiple myeloma, as an oncogene, has been widely recognized for its high expression levels in various malignant tumors." (PMID 40535130, 2025). "Myeloma overexpressed gene (MYEOV) was initially identified as a gene amplified in several malignancies and was found to promote cell proliferation and metastasis." (PMID 41186354, 2025). "Recent research has unveiled MYEOV as a novel transforming gene, initially discovered in the 11q13 chromosomal region in myeloma." (PMID 40535130, 2025). "Within the professional domain, MYEOV (myeloma overexpressed gene) has been widely reported as an oncogene that is overexpressed in multiple myeloma." (PMID 40535130, 2025). "MYEOV plays a significant role in multiple malignancies, particularly in diseases such as multiple myeloma, breast cancer, lung cancer, pancreatic cancer, and esophageal cancer." (PMID 40535130, 2025). "MYEOV is involved in the pathogenesis of a variety of cancers, including multiple myeloma, neuroblastoma, esophageal cancer, breast cancer, lung cancer, gastric cancer, and colorectal cancer." (PMID 40535130, 2025). "The myeloma overexpressed gene (MYEOV) has been proposed to be a proto-oncogene due to high RNA transcript levels found in multiple cancers, including myeloma, breast, lung, pancreas and esophageal cancer." (PMID 39139450, 2024). "MYEOV (MYEloma Overexpressed gene) was initially identified as a potential oncogene in specific multiple myeloma cell lines." (PMID 37792852, 2023). "Specifically, TNFSF13B expression had close interactions with macrophage marker genes, namely, TLR and S100A9 genes; their receptor genes, TNFRSF13B and TNFRSF17, showed significant associations with the myeloma-related genes CD38, SDC1, and MYEOV." (PMID 34150664, 2021). "Compared to the MGUS, MM patients were characterized by an evident rise in MYEOV+ myeloma cells, in which a clear upregulation of TNFSF13B receptors, TNFRSF13B and TNFRSF17, was detected." (PMID 34150664, 2021). "By partially controlling the proliferation of MMC, MYEOV gene expression was used as a prognostic factor in patients with multiple myeloma." (PMID 34169093, 2021). "Myeloma overexpressed (MYEOV) acted as an amplified competing endogenous RNA in promoting metastasis by activating TGF-β pathway in non-small cell lung cancer and served as the potential therapeutic target." (PMID 33708105, 2020). "Myeloma overexpressed gene (MYEOV) is located on chromosome 11q13, this region has been reported to have frequent DNA amplification." (PMID 32340320, 2020). "Cancers showing overexpression of MYEOV transcripts include multiple myeloma, breast cancer, esophageal squamous cell carcinomas, gastric cancer, colon cancer, neuroblastoma and, more recently, pancreatic ductal adenocarcinoma (PDAC) and non-small cell lung cancer (NSCLC)." (PMID 39139450, 2024). "Finally, we integrated the results to obtain the significantly differentially expressed gene, MYEOV (myeloma overexpressed gene), most strongly related to survival in pancreatic cancer." (PMID 36358856, 2022). "MYEOV (myeloma overexpressed) in the model can be useful as an independent prognostic marker and may become novel therapeutic targets." (PMID 34659542, 2021).
breast carcinoma (9 papers, 2015 to 2025). "Up-regulated MYEOV is associated with poor prognosis has been verified in many carcinomas, including esophageal squamous cell carcinoma, breast cancer in addition to NSCLC." (PMID 32340320, 2020). "In specific subsets of esophageal squamous cell carcinoma, breast cancer, gastric cancer, neuroblastoma, and colorectal cancer, the MYEOV gene is co-amplified and overexpressed with the CCND1 gene." (PMID 40535130, 2025). "For example, three loci—MYEOV (rs10737153), TNS1 (rs201030469) and FGFR2 (rs17102399)—have impacts on both PRC layer thickness and risk of diagnosis for breast cancer." (PMID 36848389, 2023). "The SNP rs614367 is located in an intergenic region with multiple flanking genes, including CCND1, MYEOV, ORAOV1, FGF19, FGF4 and FGF3, all of which are potential breast cancer susceptibility genes." (PMID 30247654, 2019). "The region contains CCND1 and other potential oncogenes such as FGF3, FGF4 and MYEOV and there is good evidence that this region is relevant to breast cancer." (PMID 28095868, 2017). "Furthermore, among 150 breast cancer risk regions identified by genome-wide association studies, several ERGs identified in this study (BARX2, CBX6, KCNN4, MYEOV, PDZK1 in 300 ERGs) were included as the targets for cancer drivers, transcription factors, and signaling proteins." (PMID 35976950, 2022). "A few over-expressed genes in cancer are also located in the amplified region of 11q13.3, including MYEOV (myeloma over expressed), ORAOV1 (oral cancer over expressed gene 1), ANO1 in head and neck squamous cell carcinoma, and CTTN in breast cancer and squamous cell carcinomas of the head and neck." (PMID 26386145, 2015).
pancreatic cancer (9 papers, 2016 to 2025). "Cox proportional hazards analysis revealed that high expression of MYEOV was significantly associated with poor survival and was an independent prognostic factor for disease-specific survival in pancreatic cancer patients." (PMID 36698109, 2023). "It was found that high expressed MYEOV was significantly associated with shorter survival in pancreatic cancer patients, both in OS (p = 2.3 × 10−6), DSS (p = 3.5 × 10−7), DFI (p = 0.063), and PFS (p = 1.7 × 10−4)." (PMID 36358856, 2022). "The results of survival analysis in the ICGC database for pancreatic cancer patients also showed that high MYEOV expression was indeed significantly associated with shorter OS." (PMID 36358856, 2022). "A necroptosis-relevant risk model was developed for predicting pancreatic cancer survival and responses to immuno- and chemotherapy, comprising MYEOV, HDAC4, TLDC1, PITPNA, FNDC3B, HMGXB4, and BAX." (PMID 35662734, 2022). "Recent investigations have demonstrated that the overexpression of MYEOV is associated with poor prognosis of pancreatic cancer patients." (PMID 34659542, 2021). "Studies have indicated that MYEOV is a key gene associated with acidosis markers, with elevated expression levels in pancreatic cancer (PC) tumor tissues compared to normal tissues, and this increased expression is closely related to poor clinical outcomes in patients with pancreatic cancer." (PMID 40535130, 2025). "MYEOV is considered an independent prognostic factor for several types of human cancer, including pancreatic cancer, and a “viable” therapeutic target." (PMID 40535130, 2025). "MYEOV can enhance the DNA-binding activity of SOX9 in pancreatic cancer tissue, thereby promoting the progression of pancreatic cancer." (PMID 40535130, 2025). "In conclusion, we showed that MYEOV suppression is a new mechanism that contributes to a poor prognosis in pancreatic cancer patients through the activation of the folate cycle and the c-Myc and mTORC1 pathways." (PMID 36698109, 2023). "We also examined the expression level of MYEOV in pancreatic cancer cell lines by qPCR and found that it was higher in several pancreatic cancer cell lines than in normal pancreatic tissues." (PMID 36698109, 2023). "This is consistent with the results of the analysis showing that MYEOV promoter methylation is maintained in some pancreatic cancer specimens at levels comparable to those in normal pancreatic tissues." (PMID 36698109, 2023). "Our data suggest that the suppression of MYEOV expression is a new factor leading to a poor prognosis in pancreatic cancer patients through activation of c-Myc and mTORC1 and metabolic remapping, such as enhancement of the one-carbon metabolic pathway." (PMID 36698109, 2023). "MYEOV enhances the activation of several oncogenic pathways, resulting in the induction of pancreatic cancer cell proliferation." (PMID 36698109, 2023). "The qPCR results showed that the expression of MYEOV was upregulated in some pancreatic cancer cell lines compared to normal pancreatic cells." (PMID 36698109, 2023). "In TCGA dataset of pancreatic cancers, the absolute value of correlation coefficients between MYEOV and MXD or CASTOR4 expression are around − 0.2." (PMID 36698109, 2023). "There is a significant correlation between elevated MYEOV expression and poor disease-specific survival in pancreatic cancer patients." (PMID 36698109, 2023). "Conversely, in pancreatic cancer cells, MYEOV expression is upregulated and promotes the downregulation of MXD4 and CASTOR2, resulting in the activation of c-Myc and mTORC1 and tumor progression." (PMID 36698109, 2023). "Recently, two groups reported that pancreatic cancer patients with higher MYEOV expression showed shorter overall survival." (PMID 36698109, 2023). "In this report, we show that the expression of MYEOV is upregulated in pancreatic cancer and that upregulation of MYEOV is significantly correlated with shorter disease-specific survival." (PMID 36698109, 2023).
pancreatic cancer (continued). "Considerably increased MYEOV expression was found in all four pancreatic cancer cells relative to HPDE cells." (PMID 36358856, 2022). "We validated the survival differences between patients with high and low MYEOV expression using log-rank tests in pancreatic cancer patients by the GSCA database." (PMID 36358856, 2022). "Although MYEOV has been found to have a promotive effect on pancreatic cancer, it still cannot fully explain the survival-related specificity of MYEOV in pancreatic cancer upregulated genes." (PMID 36358856, 2022). "We confirmed that MYEOV expression was dramatically increased in pancreatic cancer tissues relative to normal tissues." (PMID 36358856, 2022). "Given the specificity of the MYEOV gene we identified, we innovatively explored the regulatory role of MYEOV as a ceRNA for various pancreatic cancer key genes." (PMID 36358856, 2022). "Experimental verification by qRT-PCR confirmed that transcription levels of MYEOV mRNA markedly increased in pancreatic cancer cells relative to normal human pancreatic ductal epithelial cells (HPDE)." (PMID 36358856, 2022). "To identify genes critical for pancreatic cancer, we filtered and focused on the candidate gene MYEOV by combining diverse differential gene expression analyses and COX survival analysis for pancreatic cancer and normal pancreatic tissues." (PMID 36358856, 2022). "Although PDCD4 showed an opposite decrease in pancreatic cancer tissues, it was consistent with the trend of MYEOV expression in different stages of pancreatic cancer." (PMID 36358856, 2022). "To investigate the function of MYEOV in pancreatic cancer cells, we effectively knocked down MYEOV by siRNAs in CFPAC." (PMID 36358856, 2022). "For instance, MYEOV upregulation is linked with undesirable survival outcome of pancreatic cancer, which elevates the HES1 expression and triggers pancreatic cancer progression through enhancing SOX9 trans-activity." (PMID 35662734, 2022). "Overall, we identified the key position of MYEOV in pancreatic cancer by multiplex analyses and proposed the core ceRNA network of MYEOV for the first time." (PMID 36358856, 2022). "These experiments showed that the knockdown of MYEOV drastically inhibited pancreatic cancer cell proliferation." (PMID 36358856, 2022). "ANLN and MYEOV are involved in the progress of pancreatic cancer and are expected to become new markers and therapeutic targets in the future." (PMID 34394706, 2021). "Then, we screened ANLN and MYEOV related to prognosis and the immune microenvironment in pancreatic cancer." (PMID 34394706, 2021). "Knockdown of MYEOV decreased the proliferation of several pancreatic cancer cell lines." (PMID 36698109, 2023). "In this study, we report that MYEOV expression is significantly upregulated at the transcriptional level in pancreatic cancer tissues and that the expression of MYEOV is a prognostic indicator that correlates with shorter disease-specific survival independent of lymph node metastasis." (PMID 36698109, 2023). "To confirm the roles of MYEOV in pancreatic cancer cells, we knocked down MYEOV using siRNAs." (PMID 36698109, 2023). "Besides, we also identified that infiltrated immune cells are potential mediators for the molecules in the MYEOV-related network to promote pancreatic cancer progression." (PMID 36358856, 2022). "MYEOV promotes pancreatic cancer progression by increasing HES1 expression and SOX9 transactivity." (PMID 35077391, 2022). "Our results also indicated that the effect of MYEOV on pancreatic cancer progression could be based on its ceRNA role." (PMID 36358856, 2022). "Similarly, for ANLN and MYEOV, we need more external data and experiments to prove that they are related to the prognosis and immune microenvironment of pancreatic cancer." (PMID 34394706, 2021). "Correlation analysis between ANLN and MYEOV and immunomodulators showed that ANLN and MYEOV may have potential value in pancreatic cancer immunotherapy." (PMID 34394706, 2021).
pancreatic cancer (continued). "Therefore, repression of MXD4 expression by MYEOV may facilitate the malignant transformation of pancreatic cancer through activation of c-Myc and other proteins." (PMID 36698109, 2023). "Furthermore, MYEOV may be a prognostic biomarker and serve as an ‘actionable’ therapeutic target for pancreatic cancers." (PMID 36698109, 2023). "BAX, FNDC3B, HDAC4, HMGXB4, MYEOV, and TLDC1 displayed upregulated expressions in pancreatic cancer than normal tissues." (PMID 35662734, 2022). "To better investigate how MYEOV, GPRC5A, and KRAS act together in pancreatic cancer, we utilized the String database, a dedicated database for studying protein interaction networks." (PMID 36358856, 2022). "Through a multiplex analysis approach, we explored that MYEOV has a positively correlated expression relationship with GPRC5A and KRAS, and further developed a molecular network of pancreatic cancer-related genes centered on MYEOV." (PMID 36358856, 2022). "The protein expression levels of MYEOV, GPRC5A, and KRAS showed a consistent trend in pancreatic cancer tissues and normal tissues adjacent to pancreatic cancer from three pancreatic cancer patients." (PMID 36358856, 2022). "It was found that MYEOV, GPRC5A, SERPINB5, KRAS, EGFR, and EIF4G2 were all significantly elevated in pancreatic cancer tissues, and the expression trends of GPRC5A, SERPINB5, KRAS, EGFR, and EIF4G2 in different stages were nearly identical." (PMID 36358856, 2022). "We analyzed mRNA expression levels of MYEOV, GPRC5A, KRAS, EGFR, SERPINB5, EIF4G2, and PDCD4 in pancreatic cancer tissues and normal tissues adjacent to pancreatic cancer from three pancreatic cancer patients." (PMID 36358856, 2022). "The knockdown of oncogenes MYEOV and DDX60L inhibited the expression of CXCL2 in pancreatic cancer cells." (PMID 34789165, 2021). "We investigated the expression of these potential oncogenes (MYEOV, KCNN4, FAM83A, S100A16, and DDX60L) in the pancreatic cancer cell lines of the Cancer Cell Line Encyclopedia (CCLE) database." (PMID 34789165, 2021). "MYEOV promotes pancreatic cancer progression by enhancing transactivity of SOX9, a tumorigenic gene of pancreatic cancer." (PMID 34659542, 2021). "This is consistent with our results that MYEOV promotes pancreatic cancer primarily through ceRNA function independent of protein-coding capacity." (PMID 36358856, 2022). "Interestingly, the five genes identified in this study (DDX60L, FAM83A, KCNN4, MYEOV, and S100A16) showed some similar characteristics; they were highly expressed and corelated with poor prognosis in pancreatic cancer." (PMID 34789165, 2021). "It is the first report to focus on the possibility that MYEOV may act as a ceRNA to form an interaction network with some pancreatic cancer-related genes such as KRAS and serve as a strategic therapeutic target of pancreatic cancer treatment." (PMID 36358856, 2022). "It was noted that MYEOV could serve as a ceRNA by producing molecular sponging effects on hsa-miR-103a-3p and hsa-miR-107, thus affecting the role of GPRC5A, SERPINB5, EGFR, KRAS, EIF4G2, and PDCD4 on pancreatic cancer progression." (PMID 36358856, 2022). "To investigate whether MYEOV acts as ceRNA to exert certain regulatory effects on genes such as GPRC5A, SERPINB5, KRAS, EGFR, EIF4G2, and PDCD4, we analyzed the differential expression of these genes in pancreatic cancer and normal pancreatic tissues by the GEPIA database." (PMID 36358856, 2022). "It is the first report to focus on the possibility that MYEOV may act as a competing endogenous RNA (ceRNA) to form an interactive network with some pancreatic cancer-related genes such as KRAS and serve as a key therapeutic target of pancreatic cancer treatment." (PMID 36358856, 2022). "The results showed that MYEOV, KCNN4, S100A16, and DDX60L are highly expressed in most pancreatic cancer cell lines, but FAM83A is not." (PMID 34789165, 2021).
non-small cell lung carcinoma (6 papers, 2019 to 2025). A group of at least three distinct histological types of lung cancer, including non-small cell squamous cell carcinoma, adenocarcinoma, and large cell carcinoma. "In non-small cell lung cancer, MYEOV transcripts bind to mRNA, enhancing the repressive activity of the TGF-β signal, ultimately leading to further cancer progression." (PMID 40535130, 2025). "MYEOV is largely upregulated and stimulates tumor development in several human cancers, such as gastric, colon, and non-small cell lung cancers (NSCLC) 34-36." (PMID 38169540, 2024). "A study has revealed that MYEOV functions as a competing endogenous RNA (ceRNA) to promote non-small cell lung cancer through the TGF-β signaling pathway." (PMID 36358856, 2022). "Previous reports suggest that the expression of MYEOV is enhanced in non-small-cell lung cancer and colorectal cancer and promotes cancer cell proliferation and invasion." (PMID 31828095, 2019). "A previous study found that MYEOV does not express proteins in non-small cell lung cancer but acts as a ceRNA to activate the TGF-β pathway to promote the biogenesis of lung cancer." (PMID 36358856, 2022).